FSCN1 (fascin actin-bundling protein 1)
Description:
Actin-binding protein that contains 2 major actin binding sites. Organizes filamentous actin into parallel bundles. Plays a role in the organization of actin filament bundles and the formation of microspikes, membrane ruffles, and stress fibers. Important for the formation of a diverse set of cell protrusions, such as filopodia, and for cell motility and migration. Mediates reorganization of the actin cytoskeleton and axon growth cone collapse in response to NGF.
Synonyms: HSN; SNL; p55; FLJ38511
Tractability: Small molecule: a structure with a bound ligand is known; a high-quality ligand is known. PROTAC: UniProt records ubiquitination sites on it; ubiquitination databases record sites on it; its protein half-life has been measured; a small molecule that binds it is known.
Target class: Structural protein
Gene: Protein-coding gene on chromosome 7 (5,592,809 to 5,606,655, forward strand). Ensembl gene ENSG00000075618.
Subcellular location: Cytoplasm, cytosol; Cytoplasm, cell cortex; Cytoplasm, cytoskeleton; Cytoplasm, cytoskeleton, stress fiber; Cell projection, filopodium; Cell projection, invadopodium; Cell projection, microvillus; Cell junction
Subcellular location (Human Protein Atlas): Cytosol; Plasma membrane
Pathways (Reactome):
Immune System: Interleukin-4 and Interleukin-13 signaling
Gene Ontology:
Molecular function: actin binding; actin filament binding; cadherin binding; protein binding; RNA binding; protein-macromolecule adaptor activity
Biological process: actin cytoskeleton organization; actin filament bundle assembly; cell migration; cell motility; cell-cell junction assembly; establishment of apical/basal cell polarity; microspike assembly; parallel actin filament bundle assembly; positive regulation of extracellular matrix disassembly; positive regulation of filopodium assembly; positive regulation of lamellipodium assembly; positive regulation of podosome assembly; regulation of actin cytoskeleton organization; regulation of microvillus assembly; establishment or maintenance of cell polarity; actin filament organization
Cellular component: actin cytoskeleton; anchoring junction; cell projection membrane; cell-cell junction; cytoplasm; cytoskeleton; cytosol; extracellular exosome; filopodium; microspike; microvillus; podosome; ruffle; stress fiber; growth cone; lamellipodium; cell cortex; cell leading edge
Genetic constraint (gnomAD): Loss-of-function variants: 9 observed, 30.76 expected, observed/expected ratio (o/e) 0.29, 90% interval 0.17 to 0.51. The upper end of that interval is the gene's LOEUF score, 0.51, which puts it in group 2 of 6, group 1 being the genes least tolerant of losing a copy. Missense variants: 524 observed, 667.31 expected, observed/expected ratio (o/e) 0.79, 90% interval 0.73 to 0.84. Synonymous variants: 320 observed, 297.41 expected, observed/expected ratio (o/e) 1.08, 90% interval 0.98 to 1.18.
Homologues: Orthologues: chimpanzee FSCN1 (100% identical), macaque FSCN1 (99% identical), dog FSCN1 (98% identical), guinea pig FSCN1 (97% identical), mouse Fscn1 (97% identical), rat Fscn1 (96% identical), pig FSCN1 (93% identical), zebrafish fscn1a (75% identical), tropical clawed frog fscn1 (71% identical), Drosophila melanogaster sn (40% identical). Paralogues in human: FSCN2 (57% identical), FSCN3 (27% identical).
Diseases named in the same sentence as FSCN1 in open-access papers:
FSCN1 is named in the same sentence as 146 diseases in open-access papers, as found by Europe PMC text mining. Sharing a sentence is not in itself a finding about the gene and the disease. The quoted sentences say what the papers report.
breast cancer (31 papers, 2012 to 2025). A primary or metastatic malignant neoplasm involving the breast. "FSCN1 can also serve as a diagnostic marker for distinguishing triple-negative subtypes from other breast cancer types, thyroid carcinoma from benign lesions, and uterine leiomyosarcoma from leiomyoma variants." (PMID 33614909, 2021). "In conclusion, our results demonstrate an association between FSCN1 gene variants and the risk of breast cancer." (PMID 29162880, 2017). "We also investigated the associations of these FSCN1 SNPs with clinical status, clinical pathologic markers, and susceptibility for breast cancer." (PMID 29162880, 2017). "We therefore conducted a case-control study to evaluate the role of 6 FSCN1 SNPs in breast cancer susceptibility and clinicopathological features in a cohort of Chinese Han individuals." (PMID 29162880, 2017). "This study found that breast cancer patients with the FSCN1 rs3801004 polymorphism had a higher risk of developing stage III/IV disease and lymph node metastasis." (PMID 29162880, 2017). "After that, we assessed the role of miR-133a in breast cancer cell lines and then linked miR-133a expression with FSCN1 alteration." (PMID 22292984, 2012). "However, scant information is available regarding the association between FSCN1 single nucleotide polymorphisms (SNPs) and the risk or prognosis of breast cancer." (PMID 29162880, 2017). "This study is the first to report a correlation between FSCN1 polymorphisms and breast cancer risk." (PMID 29162880, 2017). "We report on the association between 6 SNPs of the FSCN1 gene (rs56156320, rs8772, rs3801004, rs2966447, rs852479 and rs1640233) and breast cancer susceptibility as well as clinical outcomes in 316 patients with breast cancer and in 222 healthy controls." (PMID 29162880, 2017). "However, the mechanism underlying the effect of FSCN1 in the development of breast cancer, especially on TNBC, is yet to be elucidated." (PMID 29142206, 2017). "However, more research is required to determine whether an association exists among advanced-stage disease, FSCN1 expression levels and FSCN1 genotype, and clarification is needed in regard to the effects of the FSCN1 genotype on breast cancer risk." (PMID 29162880, 2017). "In addition, FSCN1 expression was associated with a number of poor prognostic characteristics in patients with IDC, suggesting that FSCN1 may be linked to the progression of mammary carcinoma." (PMID 29142206, 2017). "Fascin-1 (FSCN1) is an actin-bundling protein whose increased expression has been documented in several types of tumors, including breast cancer." (PMID 38473804, 2024). "In the present study, we investigated the expression profiles and biological effects of fascin actin-bundling protein 1 (Fascin, gene name FSCN1) in breast cancer." (PMID 35165254, 2022). "We found that compared with cancer-adjacent normal tissues, FSCN1 expression was up-regulated in a variety of tumor tissues, such as gastric cancer, breast cancer, lung cancer, and kidney cancer, in the TCGA database." (PMID 34249689, 2021). "Al-Alwan and coworkers documented that FSCN1 regulates breast cancer stem cell functions by activating the Notch and focal adhesion kinase (FAK)-β-catenin signaling pathway." (PMID 33614909, 2021). "FSCN1 expression in breast cancer has also been shown to be a key feature that supports transendothelial migration, which is a key step in the metastasis process." (PMID 34249689, 2021). "12-O-tetradecanoylphorbol 13-acetate (TPA)-induced FSCN1 gene transcription is partially mediated by the PKCδ/STAT3α signaling pathway in MCF-7 breast cancer cells." (PMID 33614909, 2021). "Previous studies showed that FSCN1 promoted breast cancer and non-small cell lung cancer progression through the MAPK pathway." (PMID 34016787, 2021). "The contrasting roles of FSCN1 in cell proliferation have also been reported in lung cancer cell A549107,108,127 and breast cancer cell MDA-MB-23145,73,76 lines." (PMID 33614909, 2021).
breast cancer (continued). "Elevated chemoresistance levels in FSCN1-positive breast cancer cells are partially mediated through the phosphatidylinositol 3-kinase (PI3K)/Akt pathway." (PMID 33614909, 2021). "Immunohistochemistry results revealed that in patients with breast cancer, the expression of Notch3 and were negatively correlated with the FSCN1 levels significantly." (PMID 33099573, 2020). "As expected, the cytoskeletal protein, FSCN1 was proved to be involved in the mechanism of metastasis of breast cancer via promoting EMT process." (PMID 33099573, 2020). "The similar results were also found in transwell assay experiments, that both of the migratory and invasive abilities of breast cancer cells were reversed by downregulating FSCN1 expression in the miR-488 inhibitor group." (PMID 33099573, 2020). "It was found that the increased Notch3 contributed to increased expression of miR-488, which further suppressed the expression of FSCN1, and corresponding proliferation, migration, and invasion of breast cancer cells." (PMID 33099573, 2020). "Both Notch3 and FSCN1 expression were statistically related to the subtypes of breast cancer divided by ER, PR, and HER2 status (p = 0.001 and 0.012, respectively)." (PMID 33099573, 2020). "miR-145 suppresses breast cancer cell migration by targeting FSCN-1 (Fascin actin-bundling protein 1) and inhibiting epithelial-mesenchymal transition." (PMID 29391441, 2018). "Further studies are therefore required to fully understand the functional roles and interactions of FSCN1 with regard to therapeutics for breast cancer, particularly for TNBC." (PMID 29142206, 2017). "This is similar to the findings in breast cancer, where overexpression of FSCN1 was correlated with invasion and predicts poor survival." (PMID 28186968, 2017). "We further analyzed the clinical aspects and rs2966447 FSCN1 genotypic frequencies in different breast cancer subtypes." (PMID 29162880, 2017). "In many human cancers including breast cancer, FSCN1 expression correlates with clinically aggressive tumors and metastasis." (PMID 28186968, 2017). "To define the potential role of FSCN1 in the progression of mammary carcinoma, we performed IHC analysis to assess the expression of FSCN1 on 125 UDH, 104 DCIS, and 467 IDC tissue samples." (PMID 29142206, 2017). "Promising results from in vitro experimental studies using docosahexaenoic acid (DHA) in breast cancer and recombinant porcine NK-lysin A in hepatocellular carcinoma have revealed that anticancer drugs targeting FSCN1 have significant potential clinical applications." (PMID 35711849, 2022). "The study documents that genetic variations in the FSCN1 gene may serve as a marker for early-stage breast cancer." (PMID 33614909, 2021). "Similarly, breast cancer in vivo models reported elevated FSCN1 expression to induce cancer cell metastasis to the lung." (PMID 34830909, 2021). "Additionally, FSCN1 maintains or increases cancer cell stemness in melanoma and breast cancer stem cells (CSCs), independently of its actin-bundling activity." (PMID 33614909, 2021). "Moreover, the stimulatory effect of FSCN1 hyperexpression on breast cancer cell metastasis is dependent on the enhancement of microtubule dynamics, not its actin-bundling activity." (PMID 33614909, 2021). "Moreover, FSCN1 expression in breast cancer cells confers resistance to chemotherapy by regulating the self-renewal abilities of breast cancer stem cells." (PMID 33614909, 2021). "It was shown that FSCN1 upregulation enhances the aggressiveness of human breast cancer." (PMID 33614909, 2021). "More studies are therefore needed to understand the roles of FSCN1 in breast cancer progression." (PMID 33614909, 2021). "Notch3 expression was strongly negative associated with FSCN1 levels in breast cancer tissues (r = −0.248, p = 0.010)." (PMID 33099573, 2020). "Thus, the current results uncover a novel molecular mechanism of the Notch3/miR-488/FSCN1 axis in breast carcinomas." (PMID 33099573, 2020).
breast cancer (continued). "Moreover, we found that XIAP 3′UTR-transfected breast cancer cells had significantly higher levels of FSCN1 and XIAP protein and mRNA compared to control cells." (PMID 28186968, 2017). "FSCN1 overexpression has been indicated in breast cancer patients." (PMID 29162880, 2017). "In breast cancer, FSCN1 expression is associated with hormone receptor-negative, more aggressive clinical course, and also associated with TNBC in African American and Chinese women." (PMID 29142206, 2017). "Taken together, these results suggested that FSCN1 could be used as a potential clinical biomarker for breast cancer." (PMID 29142206, 2017). "Our results indicate that genetic variations in the FSCN1 gene may serve as an important predictor of early-stage breast cancer." (PMID 29162880, 2017). "Inspired by above theory, we hypothesized that the XIAP 3′UTR served as a ceRNA for FSCN1 in breast cancer." (PMID 28186968, 2017). "It should be noted that FSCN1 could be expected to possess a wide range of functions in the progression of breast cancer." (PMID 29142206, 2017). "We next focused our attention exclusively on SATB1, CCND2 and FSCN1 as mediators of miR-191 and miR-425 effects, respectively, because of their strong repression obtained after miRNA expression and their reported tumorigenic function in breast cancer." (PMID 23505378, 2013). "Fascin (FSCN1) is a key regulator of breast cancer invasion." (PMID 23497265, 2013). "Next, to further explore whether the FSCN1 protein is required for miR-133a-mediated changes in breast cancer cell migration and invasion, we utilized FSCN1 siRNA to knockdown of FSCN1 expression and performed the transwell assays." (PMID 22292984, 2012). "Besides BRCA1 and BRCA2 mutations that markedly increase breast cancer risk, hundreds of low- and moderate-risk susceptibility variants have been identified, including caspase-8 (rs2293554, rs6723097,), TIMP-2 (rs7501477), and FSCN1 (rs56156320, rs3801004,)." (PMID 39614126, 2025). "Finally, FSCN1 has been reported to be overexpressed in various cancer entities including lung and breast cancer and to promote metastasis formation in colon, prostate, and oral squamous cell carcinoma by mediating the formation of filopodia and membrane protrusions." (PMID 36978029, 2023). "FSCN1 is related to numerous types of carcinomas, such as ESCC, bladder cancer, breast cancer, cervical cancer, and cholangiocarcinoma, which strongly suggests that FSCN1 might be a potential promising biomarker or therapeutic target." (PMID 35401239, 2022). "For instance, the increased expression of FSCN1 in HR-negative breast cancers might contribute to their more aggressive behavior 11, down-regulation of FSCN1 by si-RNA dramatically reduced the migratory abilities of breast cancer cells." (PMID 33753991, 2021). "Therefore, the current finding predicted miR-488 as a tumor suppressor molecule in breast cancer, and demonstrated that Notch3/miR-488/FSCN1 axis is established and involved in regulating the metastasis of breast cancers, providing novel therapeutic targets for patients with breast cancers." (PMID 33099573, 2020). "FSCN1 may serve as a predictive marker for breast cancer therapy." (PMID 29162880, 2017). "Furthermore, docosahexaenoic acid reduces FSCN1-dependent breast cancer metastasis." (PMID 29162880, 2017). "In addition, FSCN1 is involved in the chemotherapeutic resistance of breast cancer cells." (PMID 29162880, 2017). "Therefore, we further sought to determine whether FSCN1 contributed to EGF-mediated mammary carcinoma cell migration and invasion." (PMID 29142206, 2017). "MiR-133a has emerged as a tumor suppressor in non-small cell lung cancer (NSCLC), esophageal cancer (EC), prostate cancer (PC) and breast cancer (BC), targeting genes such as SOX4, EGFR, FSCN1, and COL1A1." (PMID 38504785, 2024).
breast cancer (continued). "Previous studies demonstrated anti-metastatic effects of Notch3, a transcription factor, through transcriptional up-regulation of p21, estrogen receptor-α (ERα), GATA-3, miR-488/FSCN1 and Kibra-mediated Hippo/YAP signaling in breast cancer epithelial cells." (PMID 38124049, 2023). "In breast cancer cells, GATA3 inhibits Smad4-mediated FSCN1 overexpression by suppressing the binding of Smad4 to the FSCN1 promoter." (PMID 33614909, 2021). "The primary findings of this current study provide critical insights into the crucial role of the Notch3/miR-488/FSCN1 axis in EMT and metastasis of breast cancer." (PMID 33099573, 2020). "In this study, we have investigated CTTN and FSCN1 function in EV release, using invadopodia-forming MDA-MB-231 breast cancer cells as a model cell line." (PMID 30353022, 2018). "In order to further understand the possible role of FSCN1 in TNBC, we next assessed the potential impact of FSCN1 on mammary carcinoma cell migration and invasion in TNBC cells." (PMID 29142206, 2017). "miR-145 has been reported to suppress the invasion and metastasis of breast cancer cells by directly targeting MUC1 and that of esophageal cancer cells by deregulating FSCN1." (PMID 23390502, 2013). "The loss of FSCN1 expression sensitized breast cancer cells (MDA-MB-231) to doxorubicin therapy, whereas the expression of FSCN1 in the FSCN1-negative T47-D or SK-BR-3 breast cancer cell line conferred chemoresistance." (PMID 33614909, 2021). "We performed a preliminary screen for expression levels of FSCN1 in four mammary carcinoma cell lines (contains one of the non-TNBC cell line MCF-7, and three TNBC cell lines MDA-MB-468, MDA-MB-231 and MDA-MB-453) by Real-Time Polymerase Chain Reaction (PCR)." (PMID 29142206, 2017). "In addition, the hyperexpression of FSCN1 was shown not to exhibit any significant effects on transmigration of MDA-MB-231 breast cancer cells." (PMID 33614909, 2021). "We previously generated stable MDA-MB-231 breast cancer cells with doxycycline (dox)-inducible expression of thoroughly characterized camelid nanobodies targeting CTTN SH3 or NTA domain (CTTN SH3 Nb2 or CTTN NTA Nb212,26, respectively) or FSCN1 (FSCN1 Nb512,29)." (PMID 30353022, 2018). "Furthermore, enforced expression of the miR-191/425 cluster in aggressive breast cancer cells altered global gene expression profiles and enabled us to identify important tumor promoting genes, including SATB1, CCND2, and FSCN1, as targets of miR-191 and miR-425." (PMID 23505378, 2013). "Additionally, we found that four of these sEV surface proteins (CTTN, FSCN1, ICAM1, MMP14) were exclusively present in sEVs from high invadopodia activity cells, which have previously been reported in sEVs that are preferentially secreted from invadopodia in breast cancer cells." (PMID 37014551, 2023). "Considering that there were only 6 FSCN1 negative cases in our collection, we further analyzed 91 TNBC patients from 1105 samples of TCGA breast cancer database." (PMID 29142206, 2017).